IFITM3 (interferon induced transmembrane protein 3)
Diseases named in the same sentence as IFITM3 in open-access papers (continued):
Sharing a sentence is not in itself a finding about the gene and the disease.
infection (continued). "In two cases, Vpr was associated with greater IFITM3 expression, likely due to increased infection in the culture." (PMID 32726944, 2020). "The importance of IFITM3 during HRSV infection was reflected in the increased disease severity observed in IFITM3-deficient mice following infection with HRSV." (PMID 33276587, 2020). "IFITM3 WT strongly protected cells from infection, but G91L resulted in a partial loss of virus restriction while G95L and G95W resulted in a more substantial loss of restriction." (PMID 33112230, 2020). "IFITM3 is a cellular restriction factor that inhibits infection by the influenza virus and many other pathogenic viruses." (PMID 31073529, 2019). "Overexpressed IFITM3 potently inhibits influenza virus infection, and IFITM3 KO cells are highly susceptible to infection." (PMID 30662816, 2018). "Chikungunya virus infection in the footpad caused increased ankle joint swelling in IFITM3 KO versus WT mice, correlating with increased virus burden in the serum, spleen, and ankle early in infection [41•]." (PMID 30662816, 2018). "Remarkably, IFITM3 KO cells remain highly susceptible to influenza virus infection even after IFN treatments that make WT cells refractory to infection." (PMID 30662816, 2018). "In the early stages of infection, IL-6 was the key driver of virus-induced weight loss in WT and Ifitm3–/– mice and impinged on cellular antiviral immunity." (PMID 28240600, 2017). "To further assess the potential risk of IFITM3 rs12252-C variant in severe infection cases, we performed a stratified analysis using additive model, dominant model, recessive model and allelic/multiplicative model." (PMID 28713779, 2017). "Compared with the control shRNA targeting luciferase, the specific shRNAs caused decreased expression of IFITM1, IFITM2, or IFITM3 after ATMUV infection, respectively." (PMID 28473814, 2017). "Here, IL-6R blockade halved the loss of weight in Ifitm3–/– mice seen during the first 4 days of infection." (PMID 28240600, 2017). "IFITM3 KO DC were more susceptible to infection compared to control cells at all the tested virus doses, but especially when a low virus inoculum was used." (PMID 26600246, 2015). "Conversely, pre-existing immunity from past infections or vaccination against seasonal influenza allows adaptive immune responses, such as cytotoxic T cells and antibodies, to dominate, effectively compensating for IFITM3 deficiencies (65, –, 67)." (PMID 40237465, 2025). "A previous study has indicated that single nucleotide polymorphisms (SNPs) in the gene IFITM3 may reduce the antiviral activities of IFITM3, resulting in increased infection susceptibility and illness severity." (PMID 40057761, 2025). "Importantly, IFITM3 SNPs have been consistently linked to more severe outcomes in several other emergent infections, including Hantaan virus, HIV, and SARS-CoV-2." (PMID 40237465, 2025). "Similarly, IFITM3 SNPs are reported to be risk factors for increased severity in other emergent infections, including SARS-CoV-2, Hantaan virus, and HIV." (PMID 40237465, 2025). "Similarly, our results indicate that IFITM3 deficiency also relaxes the infection bottleneck present at initial inoculation." (PMID 39477971, 2024). "This study highlights that IFITM3 deficiency lowers the minimum infectious dose of influenza virus, enhances adaptation of influenza viruses to a new host species, and broadly increases infection of human cells by avian and swine influenza viruses." (PMID 39477971, 2024). "However, lungs of Ifitm3−/− mice contained 10-fold higher levels of replicating virus than the WT mice at 6 days post-infection and this was associated with profound morbidity." (PMID 33810083, 2021).
infection (continued). "Previous studies have reported that single nucleotide polymorphisms (SNPs) of the IFITM3 gene are associated with the expression level and length of the IFITM3 protein and can impact susceptibility to infectious viruses and the severity of infection with these viruses." (PMID 34828268, 2021). "Importantly, a recent study demonstrated that mutations in distinct regions of IFITM3 regulate its inhibitory vs enhancing activity against infection by different coronaviruses." (PMID 30640957, 2019). "In addition, the CC genotype was estimated to confer a six-fold increased risk for severe infection than the CT and TT genotypes, reinforcing the idea that IFITM3 is a factor affecting human IAV disease." (PMID 31574965, 2019). "The relevance of the IFITM3-mediated inhibition of IAV infection received strong support when it was shown that IFITM3 polymorphisms correlated with the severity of IAV disease in human infection." (PMID 31212878, 2019). "This rule is highlighted by the finding that mutation of IFITM3 endocytic signal results in its cell surface accumulation and gains a function to restrict the infection of human parainfluenza virus 3 (HPIV-3), which enters cells via direct fusion with the plasma membrane." (PMID 30687247, 2018). "IFITM3 has been suggested to be associated with infection in some ethnic groups." (PMID 29121968, 2017). "Furthermore, we found that productive viral replication following infection of all cell types examined was also unaffected by IFITM3 deficiency." (PMID 28240600, 2017). "In addition, deletion of one of these genes alone, Ifitm3, made mice equally susceptible to infection, showing that the Ifitm3 protein plays a central role in the control of influenza A virus in living animals." (PMID 22969429, 2012). "Finally, a study of critically ill children also linked infection severity to the IFITM3 SNP." (PMID 40237465, 2025). "This suggests that IFITM3 deficiency may promote viral adaptation by allowing adaptive variants to more efficiently outcompete other viruses in the quasispecies, perhaps by allowing infection of more cells per animal as our in vitro experiments would suggest." (PMID 39477971, 2024). "Despite the fact that NDFIP2 can exert additional effects on the virus life cycle, these results along with the decreased levels of accumulation of IFITM3 support the hypothesis that NDFIP2 at least partly regulates the cell susceptibility to infection via its role in IFITM3." (PMID 37896772, 2023). "In experiments with human monocytes, we demonstrated that IFITM3 expression affected susceptibility of cells to IAVs with conformationally stable HA molecules and that the impairment of infection in monocytes by IAVs with stable HA could be overcome by siRNA knock down of IFITM3 in these cells." (PMID 35359920, 2022). "To assess the antiviral protection conferred by endogenous IFITM1 and IFITM3 against viruses fusing at endolysosomal membranes, we measured cellular infection by influenza A virus." (PMID 42262132, 2026). "While individual knockdown of IFITM1 or IFITM3 significantly increased infection, combined knockdown of both IFITM1 and IFITM3 boosted infection to a much greater extent." (PMID 42262132, 2026). "Hemagglutination inhibition and neutralizing antibody assays on serum collected at day 18 post infection (p.i.)demonstrated production of influenza virus-specific antibodies in infected IFITM3 KO animals." (PMID 40501891, 2025). "Early work on IFITM3 showed that it effectively inhibits infection by viruses that enter cells via endocytosis, such as influenza virus and Dengue virus, but does not inhibit murine leukemia virus or Sendai virus that fuse with the plasma membrane." (PMID 40237465, 2025). "Amphotericin B treatment has been shown to restore infection of many viruses that are restricted by IFITM3." (PMID 40871241, 2025).
infection (continued). "The impact of IFITM3 on PEDV entry was assessed by measuring the intracellular levels of the viral genome at various time points post-infection." (PMID 40353666, 2025). "IFITM3 expression was positively regulated by STAT1 during infection, whereas IFITM3 knockdown increased STAT1’s compensatory effect." (PMID 40681213, 2025). "The immunofluorescence result showed that LC3B levels increased at 24 h post-infection (hpi), whereas IFITM3 knockdown inhibited the expression of LC3B." (PMID 40681213, 2025). "Host factors, including TIM-1, FHL1, and TSPAN9, are known to facilitate CHIKV entry and promote infection, whereas others, such as IFITM3, inhibit viral adsorption by limiting membrane fusion and virion internalization." (PMID 39917312, 2025). "Interferon-induced transmembrane protein 3 (IFITM3) is an antiviral effector protein that is upregulated by interferon cytokines and has been demonstrated to inhibit cell infection by a broad spectrum of viruses." (PMID 40909948, 2025). "While prior studies on IFITM3-deficient humans and mice have reported inconsistent effects on antibody responses 26, 33, 34, we observed that IFITM3 KO mice develop functionally effective adaptive immune responses following both infection and vaccination." (PMID 40501891, 2025). "The continuous expression of IFITM3 can maintain the long-term survival of lung-resident memory T cells and protect the body from infection when exposed to viruses." (PMID 40681213, 2025). "IFITM3 inhibits hMPV by blocking the virus fusion with host cell membranes via the hMPV F protein, and importantly, altering the level, localization, or activity of IFITM3 in cells can significantly affect hMPV infection." (PMID 40235933, 2025). "Here, we examined IFITM3 KO mice for their ability to develop functionally protective adaptive immune responses following infection or intramuscular vaccination with influenza virus HA antigen." (PMID 40501891, 2025). "AmB has been known to enhance infection of IAV by preventing IFITM3-mediated restriction, as well as hepatitis E virus, SARS-CoV, and SARS-like coronaviruses." (PMID 40464579, 2025). "Further, we observe significantly decreased viral titers in vaccinated IFITM3 KO compared to WT upon challenge infection, indicating that a functionally effective adaptive immune response can be generated in the absence of IFITM3." (PMID 40501891, 2025). "As such, IFITM3 limits infection by a multitude of enveloped viruses in vitro, including influenza virus, Zika virus, and SARS-CoV-25,13–15." (PMID 39477971, 2024). "While a significant increase in viral RNA copies was observed in IFITM3 silencing cells compared to control silencing cells at 8 h post infection." (PMID 38668245, 2024). "It has been shown that IFITM3 depletion profoundly decreases the antiviral processes in virus-infected cells and overexpression of IFITM3 increases resistance to infection with influenza A viruses." (PMID 38203797, 2024). "In the case of HIV-1 restriction, it has been demonstrated that target cells expressing IFITM2 and IFITM3 on their membranes can protect themselves from infection by inhibiting the fusion between the viral envelope and the cellular membrane." (PMID 38400030, 2024). "We observed that Ifitm1, Ifitm2, Ifitm3, Ifitm5 and Ifitm6 were highly upregulated during NF1_LV infection while only Ifitm1, Ifitm3, Ifitm6 were upregulated during NF45_HV exposure and at a lower level." (PMID 39735262, 2024). "Surprisingly, an average of 2.5-fold increase in SVA VP2 expression was observed in IFITM3 overexpressing cells compared to pQCXIP at 24 h after SVA isolate SD15-26 infection." (PMID 38668245, 2024). "Surprisingly, we found that IFITM2/3 was increased with DEHP treatment, and genetically silencing IFITM2 and IFITM3 significantly reduced infection." (PMID 39772131, 2024).
infection (continued). "First, IFITM3 raises the minimum infectious dose of influenza virus required to achieve a detectable infection in human cells, as well as a productive infection in vivo." (PMID 39477971, 2024). "Specifically, Ifitm3−/− animals showed significant replication of the virus in their lungs after infection with only 1 TCID50 of H5N1 or H7N3 virus, while titers were undetectable in WT lungs when infected at the same dose." (PMID 39477971, 2024). "Studies have shown that high expression of IFITM3 can be induced in a variety of immune organs after ARV infection, which is generally consistent with the trend found for the expression of ARV." (PMID 38543696, 2024). "To continue to explore the potential role of IFITM2 and IFITM3 in CHIKV-IOL infection specifically, we took advantage of the fact that CHIKV-IOL can infect hCFs, which also expresses IFITM3 at the RNA level." (PMID 39314478, 2024). "While IFITM3 inhibited infection by all the influenza viruses in all cell types in our experiments, we observed that the degree of inhibition varied to some extent depending on the individual viruses." (PMID 39477971, 2024). "IFITM3 silencing enhanced the expression of SVA capsid protein VP2 by an average of 1.94-fold at 24 h after SVA isolate SD15-26 infection (p < 0.001)." (PMID 38668245, 2024). "For example, IFITM3 alters the function of late endosomal compartments, thus slowing rotavirus to escape from endosomes and limiting infection." (PMID 38793616, 2024). "Increased infection was also observed for IFITM3 KO HAP1 fibroblasts and for IFITM1/2/3 KO HeLa cells." (PMID 39477971, 2024). "IFITM3 is known to play a role in restricting infection by some viruses and bacteria, such as SARS-CoV-2 and Mycobacterium tuberculosis." (PMID 37100873, 2023). "Remarkably, as infection progressed (24 h p.i.), IFITM3 remained increased only in LSD1-overexpressing cells." (PMID 37947646, 2023). "In an overexpression screening of functional ISGs, human IFITM2 and IFITM3 inhibited SARS-CoV-2 spike pseudotype infection, while overexpression of IFITM1 reduces spike-mediated cell–cell fusion." (PMID 36992348, 2023). "The results revealed a significantly higher infection level in cells with IFITM3 knockdown than in control knockdown cells." (PMID 37100873, 2023). "(G) Representative images of IFITM3 immunofluorescence in brain organoids with microglia with wild type RV or heat-inactivated control 72 hr post-infection." (PMID 37470786, 2023). "Interferon-induced transmembrane proteins (specifically IFITM-1, IFITM-2, and IFITM-3) have been previously shown to be induced following the infection of viruses, ranging from Influenza A to Ebola to HIV." (PMID 36298693, 2022). "While cardiac function in WT mice was largely unchanged throughout infection, IFITM3 KO mice showed depressed heart rates during the course of infection with PR8-miRctrl." (PMID 35544568, 2022). "It was shown that there was background IFITM3 expression in Caco2 cells, which was further induced after infection." (PMID 36366505, 2022). "siRNA-mediated knockdown of IFITM3 in HSAEC resulted in enhanced VSV-CoV-2 infection, indicating that IFITM3 restricts Spike-mediated infection in these cells." (PMID 33880473, 2022). "One study showed that endogenous expression of IFITM3 promotes efficient infection by SARS CoV231, while another study demonstrated that IFITM3 possesses both pro and antiviral effects against SARS CoV232." (PMID 36153346, 2022). "For these experiments, both hepatoma cell lines HepG2-NTCP and HuH7-NTCP, as well as PHH, were transiently transfected with IFITM3 siRNA and control siRNA, and infection was performed by inoculation with 5 × 109 HBV genomes/well or with 2–4 × 105 HDV IU/well." (PMID 35458456, 2022). "We performed electrocardiogram (ECG) measurements on WT and IFITM3 KO mice before infection and at several time points after infection with PR8-miRctrl or PR8-miR133b/206." (PMID 35544568, 2022).
infection (continued). "Transcripts of effector IFN-induced cell membrane proteins IFITM2 and IFITM3 are increased throughout the infection time course." (PMID 35443155, 2022). "Infection of human MKs with DENV selectively increased type I and IFITM3 interferons, and overexpression of IFITM3 was sufficient to prevent infection." (PMID 35842415, 2022). "siRNA-mediated knockdown of IFITM3 in hSAECs resulted in enhanced VSV-CoV-2 infection, indicating that IFITM3 restricted spike-mediated infection in these cells." (PMID 36264642, 2022). "IFITM3 overexpression alone had little effect on GPpp infection but in combination with ZMPSTE24-FLAG, we observed a significant enhancement in the restriction of LCMVpp and LASVpp infection." (PMID 35283811, 2022). "In contrast, reduced infection rates were detected for the HDV-WHO strain under IFITM3 knockdown in both cell lines, HepG2-NTCP and HuH7-NTCP." (PMID 35458456, 2022). "This correlates with resistance to an entry restriction mediated by interferon-induced transmembrane protein 2 (IFITM2) and a pronounced infection enhancement by IFITM3." (PMID 36350154, 2022). "At the same time, HeLa clones with a complete knockout of both IFITM2 and IFITM3 or the three isoforms simultaneously demonstrated the increase in the infection level by more than 20 times." (PMID 35216030, 2022). "As it is well-established that IFITM3 restricts the infection with IAV, these infection experiments served as an additional control for efficient IFITM3 knockdown in the HuH7-NTCP cells." (PMID 35458456, 2022). "Then, siRNAs targeting IFITM3 led to a 50% increase in the infection of SARS-CoV-2 S-pseudotyped virus." (PMID 36423162, 2022). "Quantitative analysis of images from multiple mice confirmed that fibrotic staining in heart samples from IFITM3 KO mice infected with miR-targeted virus was significantly decreased compared to infection with miRctrl virus." (PMID 35544568, 2022). "We thus collected hearts from WT and IFITM3 KO mice at day 10 after infection and first performed histological analysis of fibrosis using Masson’s trichrome staining." (PMID 35544568, 2022). "IFITM3 was shown to broadly inhibit infection by many enveloped viruses, including H1N1 influenza A, dengue virus (DENV), WNV, MARV, EBOV, yellow fever virus (YFV), and MERS." (PMID 35631059, 2022). "After this indirect approach via myr-preS1 peptide binding to NTCP, we aimed to directly analyze the effect of IFITM3 knockdown on the infection rates with HBV and HDV particles." (PMID 35458456, 2022). "Consistent with enhanced disease severity in IFITM3 KO mice, the KO animals lost significantly more weight than WT mice in infections with both viruses." (PMID 35544568, 2022). "Since IFITM3 impedes virus entry, we measured the effect of IFITM3 on the infection of lentiviral particles pseudotyped with SARS-CoV-2 spike protein." (PMID 36423162, 2022). "Others have also reported that IFITM1 and IFITM3 have a different tissue-specific expression pattern during H9N2 infection in BALB/c mice (Yu and others 2015)." (PMID 35708622, 2022). "In our study, the expression of IFN-α in the spleen and the expression of antiviral proteins (OASL, MX1, and IFITM3) in the spleen and kidney were increased after GNAstrV infection." (PMID 33647718, 2021). "The IFITM3 protein is the first restriction factor to be described that can prevent the infection by hMPV." (PMID 33809875, 2021). "Within this family, the IFITM3 protein prevents the infection of subgroups A1 and B1 of hMPV in vitro." (PMID 33809875, 2021). "Since IFITM3 appears to drive much of the deleterious effects of type I IFN on the host to benefit Lm during infection, it represents a possible therapeutic target for the treatment of this class of bacterial pathogens." (PMID 34404769, 2021). "In future studies, it will be important to determine if other bacterial pathogens that undergo cytosolic growth and cell-to-cell spread can also exploit IFITM3 during infection in phagocytes." (PMID 34404769, 2021).